KIAA2013 (KIAA2013)
Synonyms: MGC33867; RP5-1077B9.1
Tractability: Antibody: UniProt predicts a signal peptide or a membrane-spanning region. PROTAC: ubiquitination databases record sites on it; its protein half-life has been measured.
Gene: Protein-coding gene on chromosome 1 (11,919,591 to 11,926,428, reverse strand). Ensembl gene ENSG00000116685.
Subcellular location: Membrane
Subcellular location (Human Protein Atlas): Golgi apparatus; Cytosol
Gene Ontology:
Molecular function: protein binding
Cellular component: membrane
Genetic constraint (gnomAD): Loss-of-function variants: 20 observed, 33.08 expected, observed/expected ratio (o/e) 0.6, 90% interval 0.42 to 0.88. The upper end of that interval is the gene's LOEUF score, 0.88, which puts it in group 3 of 6, group 1 being the genes least tolerant of losing a copy. Missense variants: 587 observed, 714.5 expected, observed/expected ratio (o/e) 0.82, 90% interval 0.77 to 0.88. Synonymous variants: 336 observed, 334.36 expected, observed/expected ratio (o/e) 1, 90% interval 0.92 to 1.1.
Homologues: Orthologues: macaque KIAA2013 (95% identical), dog KIAA2013 (94% identical), mouse 2510039O18Rik (92% identical), pig KIAA2013 (91% identical), rat 2510039O18Rikl (91% identical), guinea pig KIAA2013 (87% identical), tropical clawed frog KIAA2013 (55% identical), zebrafish si:dkeyp-104h9.5 (54% identical), Drosophila melanogaster CG7289 (25% identical), Caenorhabditis elegans C17H12.2 (21% identical).